MACC1 (MET transcriptional regulator MACC1)
Diseases named in the same sentence as MACC1 in open-access papers (continued):
Sharing a sentence is not in itself a finding about the gene and the disease.
tumor (continued). "In tumor buds, a strong cytoplasmic expression was observed: 55% of the dissociated single cells or small clusters of up to five cells identified at the invasive front demonstrated MACC1 expression." (PMID 25884643, 2015). "Quantitative IHC examinations revealed that MACC1 abnormal abundance in cancerous tissues might represent a biological indicator clinically suggestive of tumor malignancy in the renal pelvis." (PMID 24949951, 2014). "Tumor malignancy was identified to correlate with MACC1 expression levels and MACC1 expression may affect the values of other prognostic factors in multivariate analysis, such as distant metastasis, which was found to be significant in univariate analysis." (PMID 25295116, 2014). "Metastasis-associated in colon cancer-1 (MACC1) was first identified as a transcriptional activator for proto-oncogene c-MET expression, and its overexpression is frequently associated with metastatic progression for multiply tumor types." (PMID 23497677, 2013). "Moreover, multivariate analysis also demonstrated that TNM staging, tumor size and MACC1 expression level are indeed predictive of the overall survival (OS) of HCC patients." (PMID 23717574, 2013). "Several studies demonstrated that, besides in CRC, MACC1 could serve as an independent prognostic marker of tumor invasiveness and metastasis in some other cancer types." (PMID 22533346, 2012). "Expression of MACC1 and invasiveness of the tumor then could be analyzed to come to a conclusion." (PMID 37627117, 2023). "The gene MACC1 is a key regulator of the HGF/c-Met pathway and its overexpression is causative for cancer cell proliferation, colony formation, dissemination, migration, and invasiveness in cell culture and for tumorigenesis, tumor progression and metastasis formation in several mouse models." (PMID 35406521, 2022). "Expression of metastasis-associated in colon cancer-1 (MACC1) gene on NPC cells and enhanced level of soluble MHC class I chain-related molecular A (MICA) is correlated with the downregulation of NKG2D surface expression on NK cells, contributing to tumor progression." (PMID 35311066, 2022). "Therefore, in this study, we investigated the effect of curcumin on MACC1-driven tumor progression." (PMID 36432477, 2022). "Finally, to further verify whether the tumor invasiveness promoted by MACC1 was dependent on MET, we treated PC cells with JNJ-38877605, a selective inhibitor of MET." (PMID 36333284, 2022). "Genetic factors might provide additional layers for MACC1 expression regulation resulting in phenotypical features of cell proliferation, dissemination, and motility, and more importantly link to tumor progression, metastasis formation, treatment response, and ultimately, to patient survival." (PMID 35406521, 2022). "This strengthens our hypothesis on MACC1-related differences in tumor uptake." (PMID 33652667, 2021). "In addition, the overexpression of MACC1 is very important for tumor metastases and poor prognosis." (PMID 34072650, 2021). "However, the relation between MACC1 and tumor-infiltrating immune cells is still unclear." (PMID 34577857, 2021). "Therefore, GLUT-1 and MACC1 may established as a suitable biomarker for predicting the tumor TNM stage of CRC patients, in order to improve individualized therapy regimen in CRC." (PMID 33750337, 2021). "In terms of hematogenous metastasis, another oncogene, namely insulin-like growth factor binding protein-2 (IGFBP2), comes into consideration, which has surprisingly neither been associated with the oncogene MACC1, nor with tumor-cell-induced platelet activation." (PMID 34830078, 2021). "On the other hand, glucose-mediated induction of MACC1 expression and the fact that MACC1 expression is increased at the tumor invasive front, where glucose availability is higher than in the necrotic tumor center, may explain the increased invasiveness of MACC1 expressing cells." (PMID 33652667, 2021).
tumor (continued). "We investigate whether GLUT-1/MACC1 expression can reflect tumor glycometabolism." (PMID 33750337, 2021). "Similarly, MACC1 depletion inhibited tumor growth, metastasis, and angiogenesis in mice." (PMID 33425885, 2020). "In addition, tumors from the MACC1 group were significantly larger than those from the vector‐NC group, and overexpression of MACC1 significantly increased xenograft tumor volume (P < .05) and tumor weight (P < .05)." (PMID 31557409, 2019). "Thus, we hypothesized that YB-1 binds to the MACC1 promoter and up-regulates MACC1 expression to promote tumor cell invasion and tumor growth." (PMID 28624808, 2017). "Indeed, MACC1 was shown to be involved in many processes such as proliferation, tumor-formation ability, migration and invasiveness that might begin at pre-cancerous stages." (PMID 27439755, 2016). "We hypothesized that serum MACC1 levels may mirror BC tumor progression and invasion." (PMID 27793048, 2016). "Previously, we found that MACC1 contributed to the poor prognosis of GC and increased the resistance to metabolic stress by promoting the Warburg effect that consequently facilitated tumor progression, which elucidated its key role in signaling networks associated with GC." (PMID 27581375, 2016). "Indeed, there was ∼43.2% increase detected in tumor tissues of grade 3 when compared to grade 1 or 2, suggesting that MACC1 protein abundance may be strongly correlated with the development and progression of RPC." (PMID 24949951, 2014). "In summary, extensive research on KAI1, MACC1, and AGR2 has illustrated their involvement in tumor invasion and metastasis." (PMID 41239615, 2025). "Univariate Cox analysis was performed for 12 variables, including B3GNT3, MACC1, NELL2, USH1G, age, sex, alcohol use, tobacco use, tumor grade, T stage, N stage and pTNM stage." (PMID 38818465, 2024). "We not only showed the association of MACC1 and LGR5 expression, but also demonstrated the molecular mechanism by binding of MACC1 to the gene promoter of LGR5 initiating its expression and inducing stem cell properties like tumor sphere formation." (PMID 38339354, 2024). "B3GNT3, MACC1, and NELL2 showed significantly higher expression in normal tissues than in tumor tissues." (PMID 38818465, 2024). "While on the basis of knocking down MACC1 and continuing to knock down KLF4, the diameter of tumor cell microspheres in the shKLF4-shMACC1 group was significantly enlarged, and the number of spheres was also partially restored." (PMID 39695175, 2024). "Then, we analyzed tumor sphere formation of HCT116/GFP vs. HCT116/MACC1 and SW620/Cas9 vs. SW620/MACC1-KO cells." (PMID 38339354, 2024). "We supported this link by forced expression, knockdown or knockout of MACC1, followed by subsequent corresponding expression of stemness genes such as LGR5, as well as phenotypic features like the initiation of tumor sphere formation and clonogenicity." (PMID 38339354, 2024). "In CRC and BC, MACC1 overexpression regulates β-catenin, HGF/c-Met, and other signaling pathways to elevate tumor malignancy." (PMID 39399490, 2024). "In particular, we demonstrate an MACC1—LGR5 link by transcriptional regulation of the crucial stemness gene LGR5 by MACC1, the inducer of tumor initiation, progression and metastasis." (PMID 38339354, 2024). "High levels of serum MACC1 correlate with TNM stage (I, II, or III), lymphatic metastases, tumor size, and the Ki-67 status of BC." (PMID 36979146, 2023). "The relevance of GIPC1 for tumor growth and metastasis was shown in mice intrasplenically transplanted with MACC1-overexpressing CRC cells, since GIPC1 knockdown reduced these MACC1-induced features." (PMID 38144523, 2023). "High expression of MACC1 in BCs predicts shorter OS and RFS, poorer tumor differentiation, more advanced FIGO staging, and earlier lymph node metastasis." (PMID 36979146, 2023). "Another signaling route affected by MACC1 is the ERK pathway, as demonstrated in multiple tumor entities." (PMID 37051546, 2023).
tumor (continued). "Results from our group showed in vil-MACC1/ApcMin transgenic mice the interplay of Wnt signaling and MACC1 action for CRC tumor formation." (PMID 35406521, 2022). "At the experimental endpoint (tumor burden), the signals in the livers of FLO-1/MACC1/Luc-cell-transplanted animals (6.48 × 108 RLU) exceeded the signals of the control animals (3.29 × 108 RLU, p = 0.0823) by nearly two-fold." (PMID 35406545, 2022). "For example, MACC1 was found to regulate the expression of PDL1 and tumor immunity through the c‐Met/AKT/mTOR pathway in gastric cancer." (PMID 36545127, 2022). "Recent studies have shown that MACC1 is a key regulatory factor in the HGF/c-Met signaling pathway and is a major target for tumor invasion and metastasis." (PMID 35242498, 2022). "It would be interesting to study the correlation of MACC1 and COL10A1 activation in the analysis of bulk tumor specimen and in functional studies applying genetic COL10A loss of function models." (PMID 36267978, 2022). "The correlated expression of MACC1 and S100P was validated in publicly available microarray datasets of CRC tumours from the Gene Expression Omnibus repository." (PMID 35597866, 2022). "For OS, while MACC1 expression showed a similar trend than for DFS (p = 0.11), only the tumor stage was statistically significant (p = 0.001)." (PMID 35406521, 2022). "In univariate analysis, the factors with statistical significance were LVI, tumor stage, PR, CD163+ TAMs count, CD56+ NK cells count, and MACC1 mRNA relative expression." (PMID 34577857, 2021). "This study identifies MACC1 as new MEK1 substrate for tyrosine phosphorylation decisively impacting cell motility, tumor growth, and metastasis." (PMID 34247190, 2021). "In brief, our study suggested that MACC1/SPINT1 panel can be a reliable prognostic indicator, which provides an advance in tumor prognosis research." (PMID 33751856, 2021). "Tumor growth and liver metastases were induced in SW480/MACC1-wt-transplanted mice, confirming our previous findings." (PMID 34247190, 2021). "Previous studies postulated that MACC1 controls PDL1 expression and tumor immunity by modulation of the c-Met/AKT/mTOR pathway, hence affecting cytotoxic T-cells in BC TME." (PMID 34577857, 2021). "Taken together, MEK1-mediated MACC1 tyrosine phosphorylation is essential for MACC1 function regarding to tumor growth and metastasis, and is druggable by MEK1 inhibitors to restrict tumor growth and metastasis." (PMID 34247190, 2021). "GLUT-1 and MACC1 play an important role in tumor progression, we next to investigated the relationship between GLUT-1/MACC1 and tumor T, N and M status in primary CRC lesions." (PMID 33750337, 2021). "In this study, we detected the semi-quantitative (SUVmax, SUVmean, TLG and MTV) derived from FDG and the expression of tumor markers (GLUT-1 and MACC1) in patients with different stages of CRC which consistent with pathological results." (PMID 33750337, 2021). "Higher serum MACC-1 levels were also observed with increasing TNM stages (p < 0.0001) and tumor grade (p = 0.007)." (PMID 33400729, 2020). "Thus, a rising serum MACC-1 level may indicate tumor progression." (PMID 33400729, 2020). "Another study showed an increased MACC-1 in tumor tissue and its positive correlation with TNM stage, tumor size and nodal status." (PMID 33400729, 2020). "According to a retrospective cohort study, MACC1 is differentially expressed in CRC and predicts best aggressive clinicopathological features, tumor budding, metastasis formation and poor survival outcome." (PMID 32595704, 2020). "The tumor promoting factors MUC16, MACC1 and GRHL2 were downregulated in PitNETs after SSA/DA therapy and in GH3 cell following octreotide treatment." (PMID 33680922, 2020). "Three tumor development promoting factors MUC16, MACC1, and GRHL2, were significantly downregulated in therapy administered PitNET tissue; this finding was supported by functional studies in GH3 cells." (PMID 33680922, 2020).
tumor (continued). "We showed the interaction of MACC1 with the cancer stem cell (CSC) marker DCLK1, which contributes to metastasis formation in different tumor entities." (PMID 32756469, 2020). "When PDL1 levels were upregulated by MACC1 transfection in MKN28 cells, the MTS assay indicated that the tumor cell killing rate of the MACC1 group was significantly lower than that of the vector‐NC group (P < .05)." (PMID 31557409, 2019). "Recently, it was shown that miRNA-598 serves tumor-suppressive roles in GBM cell lines and that these effects are mediated through direct suppression of MACC1 expression." (PMID 31200581, 2019). "In summary, we demonstrate that MACC1 regulates PDL1 expression and tumor immunity through the c‐Met/AKT/mTOR pathway in GC cells." (PMID 31557409, 2019). "Using MACC1 transfection and inhibitor treatment, this study aimed to verify the relationship between MACC1 and PDL1 and examine their effects on GC tumor immunity." (PMID 31557409, 2019). "Studies have shown that tumor exosomes are involved in communication between tumor and normal cells, and help promote tumor growth and invasion through MAPK/ERK signaling and miR-338/MACC1/MET pathways, leading to changes that assist tumor progression." (PMID 30261592, 2018). "In this study, our findings indicated that positive expression of MACC1 in CAC was positively correlated with invasion and tumor differentiation and LNM and TNM stages." (PMID 30021598, 2018). "Positive expression of MACC1, CD44, and Twist1 was found to be positively correlated with invasion, tumor grades, and lymph- node-metastasis (LNM) stages and tumor-node-metastasis (TNM) stages for patients with CAC." (PMID 30021598, 2018). "The immunostaining results indicated that positive expression of MACC1 in CAC was positively correlated with invasion, tumor differentiation, LNM stages, and TNM stages." (PMID 30021598, 2018). "Both YB-1 and MACC1 regulate the HGF/c-Met signaling pathway and induce tumor invasion and metastasis in several cancer types." (PMID 28624808, 2017). "In vitro, MACC1 can activate the HGF/c-Met signaling pathway to induce EMT, which promotes tumor proliferation, invasion, and dissemination." (PMID 28253891, 2017). "As a pivotal oncogene for tumor progression influencing the HGF/c-MET pathway, MACC1, has been shown to participate in many biological mechanisms that produce poor clinical outcomes." (PMID 27581375, 2016). "In this present study, we also found miR-218 and MACC1 gene expression was significantly down- or upregulated, respectively, in CRC tumor specimens." (PMID 27462788, 2016). "MACC1 not only elevated the VEGF-A level in vitro, but also accelerated the tumor growth and induced the microvessel formation in vivo." (PMID 27280289, 2016). "There were also significant differences between the positive expression of MACC1 and tumor grade (P = 0.015), lymph node metastasis (LNM) (P < 0.001), and tumor node metastasis (TNM) (P = 0.001)." (PMID 27832750, 2016). "We found that MACC1 expression was positively correlated with an increased MVD and tumor recurrence in GC patients." (PMID 27280289, 2016). "We previously reported that MACC1 was impaired by metabolic stress via AMP-activated protein kinase (AMPK) activation, and involved in tumor energy metabolism by enhancing the Warburg effect." (PMID 27280289, 2016). "Moreover, we discovered that MACC1 was upregulated by metabolic stress in GC via adenosine monophosphate-activated protein kinase signaling, which increased the resistance to metabolic stress by promoting the Warburg effect and consequently facilitated tumor progression." (PMID 27581375, 2016). "We performed 3′-RACE experiment using the CRC tumor cell line SW620 and found that MACC1 possesses several APA sites in these cells." (PMID 27462788, 2016). "In GC xenograft models, MACC1 elevated MVD and upregulated the expression of VEGF-A as well as accelerated tumor growth." (PMID 27280289, 2016).
tumor (continued). "In this study, we investigated the relationship between MACC1 and ALDH1 expression in patient tumor sections as well as compared their expression with the clinicopathology and prognosis of NSCLC." (PMID 27832750, 2016). "To have further insights of the potential inverse miR-218- and MACC1-expression correlation in the clinical situation, we screened a cohort of CRC patient tumor specimens and representative normal mucosa samples." (PMID 27462788, 2016). "MACC1 and SOX9 show a progressive increase in tumour and metastases compared to normal tissue with a median log 2 expression value increase from 6.8 to 8.7 in normal cells, and from 8.0 to 8.8 in primary tumour cells." (PMID 27463018, 2016). "In the following analyses, MACC1 expression, normalized to GAPDH expression, in tumor tissue was calculated following division by MACC1/GAPDH expression in the normal tissue." (PMID 25295116, 2014). "As regard to tumor nuclear grade, there was also a statistically significant difference between the AOD scores of MACC1 measured in the low-grade (G1, G2: 0.0509±0.0281) and the scores measured in the high-grade RPC tissues (G3: 0.0729±0.0304) (p<0.05)." (PMID 24949951, 2014). "Consequently, our findings imply that KAI1, MACC1, and AGR2 should be regarded as valuable biomarkers for this malignancy, particularly in the context of predicting tumor metastasis and patient outcomes." (PMID 41239615, 2025). "Additionally, the expressions of MACC1 and AGR2 were positively correlated, with their overexpression collaboratively driving tumor cell proliferation, invasion, metastasis, and EMT." (PMID 41239615, 2025). "Furthermore, an inverse relationship was found between miR-143 levels and MACC1 mRNA expression in CRC tissues, further affirming the tumor-suppressing function of miR-143 in this particular cancer." (PMID 41450965, 2025). "In this study, we hypothesize that TM4SF5-targeting Ex (miR-143) can effectively deliver MACC1-suppressing miRNA to CRC cells, resulting in enhanced anti-tumor effects." (PMID 39273182, 2024). "High MACC1 expression levels, whether determined in the primary tumor or in the cancer patient’s blood, predict a reduced survival time, caused by a promotion of tumor aggressiveness and metastasis formation, even when detected in early, not yet metastasized tumor stages." (PMID 35740524, 2022). "MACC1 and VEGF family members contribute to vasculogenesis, angiogenesis and vasculogenic mimicry, and are upregulated in many cancer types, correlating to tumor stage and progression." (PMID 35406521, 2022). "Sections from exemplary tumours without metachronous metastasis showed low MACC1, as well as low S100P IHC staining." (PMID 35597866, 2022). "To evaluate the clinical significance of MACC1 in PC, we performed IHC staining on a tissue microarray comprising 99 PC samples (containing 71 pairs of primary tumor tissues and the corresponding adjacent noncancerous tissues)." (PMID 36333284, 2022). "Thus, S100P can be used as a prognostic biomarker for metachronous metastasis of CRC tumour Stages II and III, and although correlated with the expression of MACC1, their combination further refines the determination of the metastatic risk of CRC patients." (PMID 35597866, 2022). "To test whether MACC1-dependent expression of S100A4 is a clinically prevalent phenomenon in CRC, we detected both markers by IHC in representative tumor sections from a previously published cohort." (PMID 36008464, 2022). "Because the TCGA database included few normal tissue samples, data on tumor tissues in the TCGA database were combined with data on normal tissues in the GTEx database to analyze the differential expression of MACC1 in 33 tumors." (PMID 36545127, 2022). "They report a median MACC1 copy number of 3.0 in patients with tumor recurrence and 1.4 in patients without recurrence." (PMID 35406521, 2022).